MYOG (myogenin)
Diseases named in the same sentence as MYOG in open-access papers (continued):
Sharing a sentence is not in itself a finding about the gene and the disease.
rhabdomyosarcoma (continued). "These were 7 tests for h-caldesmon (for leiomyosarcoma), 3 CDK4 (for WDL/DDL), 2 DOG1 (for GIST), 2 beta-catenin (for fibromatosis), 1 each of CD34 (DFSP), desmin, myogenin (rhabdomyosarcoma (RMS)), p63 (sarcomatoid carcinoma), PSAP (prostatic carcinoma), and TLE1 (synovial sarcoma)." (PMID 25165418, 2014). "In addition, the IHC expression of muscle-specific markers such as desmin, myogenin, or myo-D1 is characteristic of rhabdomyosarcoma." (PMID 23762725, 2013). "Rhabdomyosarcoma and rhabdomyosarcomatous sarcomatoid carcinoma can be differentiated from small cell carcinoma of the bladder by immunohistochemical evaluation of cytokeratin and chromogranin and myogenin." (PMID 21762516, 2011). "Area of rhabdomyosarcoma express desmin and skeletal muscle markers, myogenin and myoD1." (PMID 21663687, 2011). "Immunohistochemically sclerosing rhabdomyosarcoma in adults shows a distinctive immunophenotype in the expression of muscle markers, characterized by positivity for MyoD1, negativity for Myogenin and variable expression for Desmin and Actin muscle specific, as occurred in the elbow tumor." (PMID 20701800, 2010). "We analyzed a much larger cohort of 49 primary rhabdomyosarcoma tumor samples of various subtypes, collected over a period of 9 years, for the presence of MYOD1 (L122R), PIK3CA (H1047), and PIK3CA (E542/E545) mutations, along with immunohistochemical analysis of desmin, myogenin, and MYOD1." (PMID 27562493, 2016). "Additionally, pPNET can be differentiated from rhabdomyosarcoma, which is positive for desmin and myogenin, and lymphoma, which may be excluded by immunostaining for LCA and other lymphohematopoietic markers." (PMID 25435942, 2015). "Myogenin (MyoG) is a core myogenic transcription factor that orchestrates myoblast differentiation and myofiber maturation and has been increasingly implicated in skeletal muscle degeneration and rhabdomyosarcoma, yet its global research landscape has not been systematically characterized." (PMID 41868599, 2026). "Some alveolar rhabdomyosarcomas can express CD99, but they also express myogenic markers, including myogenin and MyoD1." (PMID 40950824, 2025). "In immunohistochemical staining, rhabdomyosarcoma (RMS) exhibits positive expression of vimentin, desmin, myogenin, and MyoD1." (PMID 40703554, 2025). "Virtually all examples of TFCP2-rearranged rhabdomyosarcoma are diffusely positive for pancytokeratins, e.g., AE1/AE3, OSCAR, MNF116, and desmin, as well as myogenin and/or MYOD1, with MYOD1 showing higher sensitivity." (PMID 40526340, 2025). "Of note, fibroblasts can transform into skeletal muscle cells via myogenin (MYOG), indicating a potential regulatory link between metastatic OS and other musculoskeletal cancers such as rhabdomyosarcoma, as revealed by the GO analysis." (PMID 37228489, 2023). "In rhabdomyosarcoma (RMS) cells, Arp5 expression was significantly higher than in normal myoblasts and skeletal muscle tissue, probably contributing to MyoD and MyoG activity dysregulation." (PMID 35348112, 2022). "In conclusion, we generated a modified human MYOGENIN promoter by deleting MEF3 and NF1 binding sites that has enhanced specificity for rhabdomyosarcoma over skeletal myogenic cells." (PMID 32973362, 2021). "In the case of human rhabdomyosarcoma cells, it resulted in increase of MYOD1, MYOG, and MyHC expression." (PMID 34571854, 2021). "In rhabdomyosarcoma, for example, through the RAF–MEK–ERK MAPK pathway, oncogenic RAS inhibits myogenic differentiation by reducing MYOG expression, which is mediated by ERK2-dependent promoter-proximal stalling of RNA pol II at the MYOG locus." (PMID 32382065, 2020). "The tumor cells were positive for Desmin and Myogenin, while only a few cells were positive for ALDH1, suggesting that the ALDH1high cells promoted rhabdomyosarcoma and were reconstituted to incorporate the full heterogeneity." (PMID 25915760, 2015).
rhabdomyosarcoma (continued). "The negative staining for cytokeratins, desmin, myogenin, and leukocyte common antigen helps exclude carcinoma, rhabdomyosarcoma, and lymphoid malignancies, respectively." (PMID 40084340, 2025). "Rhabdomyosarcomas (RMS) are high-grade malignant tumors exhibiting partial myogenic differentiation due to aberrant expression of muscle regulatory factors (MRFs) such as myogenic factor 5 (MYF5), myoblast determination protein 1 (MYOD), and myogenin (MYOG)." (PMID 41425252, 2025). "However, the discovery of rhabdomyoblast‐like cells with positive skeletal muscle differentiation markers (Desmin, MyoD1, and Myogenin) in the stromal background, raised the possibility of alternative diagnoses, such as PIS‐DICER1 or rhabdomyosarcoma." (PMID 40040389, 2025). "The majority of soft-tissue sarcomas were myosarcomas – primarily leiomyosarcomas that were confirmed by positive desmin staining and negative myogenin staining, and rhabdomyosarcomas confirmed by positive desmin and negative myogenin staining." (PMID 41381412, 2025). "Thus, we performed IF staining of tumor sections to monitor the accumulation of rhabdomyosarcoma (RMS) markers, including MyoD1 and myogenin." (PMID 38451719, 2024). "Focal desmin positivity was seen in two of our cases but the lack of nuclear positivity for MyoD1 and myogenin ruled out a rhabdomyosarcoma." (PMID 37218666, 2024). "Spindle cell/sclerosing rhabdomyosarcoma, generally has weak to absent myogenin staining, but strong nuclear MYOD1 staining." (PMID 36173721, 2022). "Almost all rhabdomyosarcoma samples show positive nuclear staining with antibodies to MyoD1 and/or myogenin, with nonrhabdomyosarcoma pediatric tumors being consistently negative." (PMID 35372059, 2022). "Based on positive myogenin immunostaining, the pathological diagnosis was revised to rhabdomyosarcoma although the subtype was not identified." (PMID 34131151, 2021). "The spindle cells were negative for actin, desmin, Myod1, and myogenin, excluding leiomyosarcoma or rhabdomyosarcoma, and they were also negative for CD21 and CD35, excluding follicular dendritic sarcoma." (PMID 34940081, 2021). "Moreover, in PAX3-FOXO1-driven rhabdomyosarcoma, the fusion protein exploits super-enhancers to set up a CRC machinery in collaboration with the master TFs (MYOG, MYOD and MYCN); this CRC is addicted by rhabdomyosarcoma cells for survival and proliferation." (PMID 33080033, 2020). "Absence of beta-catenin or myogenin differentiates these tumors from HB and rhabdomyosarcoma, while retained INI1 differentiates it from an MRT." (PMID 32204368, 2020). "Interestingly, in rhabdomyosarcoma samples, MEF2A level positively correlated with myogenin expression, whereas myogenin level also positively correlated with myosin heavy chain 2 (MYH2A), a marker of late differentiation." (PMID 26384300, 2015). "Rhabdomyosarcoma can be differentiated from IMT based on morphological features (more frequent mitoses with atypical forms and tumor-type necrosis) and the application of an immunohistochemical panel that includes MyoD1 or myogenin." (PMID 25737794, 2015). "Rhabdomyosarcoma is often positive for smooth muscle actin, desmin, and myogenin; all of them were negative in our patients." (PMID 22312368, 2012). "We showed both rhabdomyosarcoma and rhabdomyosarcomatous areas of the urothelial carcinoma were positive for myogenin, negative for cytokeratin and chromogranin stains." (PMID 21762516, 2011). "Desmin and myogenin immunoreactivity can be used to differentiate rhabdomyosarcoma from other round cell tumors without rhabdomyoblastic differentiation but not sarcomatoid carcinoma with rhabdomyoblastic differentiation." (PMID 21762516, 2011). "Alveolar rhabdomyosarcoma was ruled out by negative myogenin and myoD1 and by absence of PAX3/PAX7-FKHR translocations by FISH." (PMID 20598147, 2010).
rhabdomyosarcoma (continued). "Bladder cancer cells were earlier demonstrated to contain both functional androgen and estrogen receptors without regard to the sex of the donor while myogenin was primary expressed in rhabdomyosarcomas." (PMID 16412233, 2006). "A final differential diagnosis could be with alveolar rhabdomyosarcoma, which can also display an alveolar pattern, but the diagnosis was ruled out by negativity of Myogenin and MyoD1 staining and no detection of PAX::FOXO1 fusion by NGS." (PMID 38643139, 2024). "In alveolar rhabdomyosarcoma, the chimeric transcription factor PAX3-FOXO1 interacts with the master transcription factors MYCN, MYOG and BRD4 at target gene super-enhancers, resulting in over-expression of SOX8, MYOD1, MYOG and MYCN, alveolar rhabdomyosarcoma tumorigenesis and dependence on BRD4." (PMID 38135679, 2023). "In addition to SMA and desmin, alveolar and embryonic rhabdomyosarcoma express MyoD1 and myogenin but not CK or neuroendocrine markers." (PMID 34193155, 2021). "Together, our data suggested that the myogenic lineage timeline is miswired in rhabdomyosarcoma to maintain early TFs (granting the self-renewal capacity afforded by the de-differentiated cell state) despite the presence of late terminal differentiation factors (prominently MYOD and MYOG)." (PMID 32416589, 2020). "Rhabdomyosarcoma was excluded by negative staining to myogenin and desmin." (PMID 22540324, 2012). "However, the lack of desmin, myogenin and MyoD-1 ruled out rhabdomyosarcoma, while LCA negativity ruled out a diagnosis of lymphoma." (PMID 20233457, 2010). "Furthermore, a large body of spindle cells showed negative reactivity for myogenin (only 2.1% of them showed positive reactivity) that has been largely accepted as a sensitive and specific immunohistochemical marker for rhabdomyosarcoma or other tumors with rhabdomyoblastic differentiation." (PMID 21329505, 2011). "Whereas lymphoma, rhabdomyosarcoma, small cell carcinoma, desmoplastic small round cell tumor and neuroblastoma were excluded by negative staining for cytokeratin, CD20, CD3, desmin, myogenin, synaptophysin and chromogranin A." (PMID 40950824, 2025). "Rhabdomyosarcoma is more common in children; the tumor cells are commonly positive for myogenic markers (such as MYOD1 and myogenin), but negative for epithelial and neuroendocrine markers." (PMID 34996495, 2022). "The tumor cells were positive for CD68, S100, CD4 and lymphocyte common antigen, while epithelial membrane antigen, HMB-45, CK AE1/AE3, myogenin, desmin, CD1a, CD21 and SALL-4 were negative thus ruling out rhabdomyosarcoma, extrarenal rhabdoid tumor, Langerhans cell sarcoma and malignant melanoma." (PMID 31890359, 2019).
sarcopenia (17 papers, 2012 to 2025). Progressive decline in muscle mass due to aging which results in decreased functional capacity of muscles. "The NUDT3 gene and myogenin expression have proven efficient as diagnostic tools for sarcopenia." (PMID 38684784, 2024). "Evaluating NUDT3 gene and myogenin expression as new diagnostic tools in sarcopenia." (PMID 38684784, 2024). "Furthermore, SP reduced ubiquitin proteasome and promoted myoblast determination protein 1 (MyoD)/myogenic factor 4 (myogenin) expression, implying that it may have potential for the treatment of obesity-induced hyperglycemia and obesity-associated sarcopenia." (PMID 32041272, 2020). "The osteoporosis model exhibited characteristic alterations in key regulatory factors of osteogenic differentiation (RUNX2), OPG, and RANKL, while the sarcopenia model demonstrated specific expression changes in MYOG and ubiquitin ligases Atrogin-1 and MuRF1." (PMID 41282482, 2025). "Based on these findings, the mRNA and protein expression levels of E3 ubiquitin ligases, known to contribute to sarcopenia (atrogin-1 and MuRF1), as well as the family of myogenic regulatory factors (MRFs) (MyoD and MyoG), were assessed in TA muscles." (PMID 38282410, 2024). "In parallel, the mRNA expression of MyoG and MyoD was significantly upregulated, whereas sarcopenia inducing E3 ubiquitin ligases that degrade muscle proteins were repressed." (PMID 38282410, 2024). "Coapplication showed a synergistic effect on suppression of type I fiber atrophy, with significantly higher IGF-1, MyoD, MyoG mRNA (p < 0.05) and pAkt protein expression (p < 0.0001) during sarcopenia." (PMID 36361730, 2022). "Collectively, our results indicate that SIN can alleviate age-related sarcopenia by increasing differentiation rate and protein levels of myoD and myogenin." (PMID 31660942, 2019). "Likewise, a recent study published by our group showed how a mixture between algae and EVOO oils also prevented sarcopenia in aged rats, an effect that was associated with a decrease in the gene expression of both HDAC-4 and myogenin in the gastrocnemius muscle." (PMID 34067004, 2021). "Furthermore, in order to elucidate the mechanisms involved in the actions of the oil mixture, we also analyzed novel factors that may play a key role in the development of sarcopenia such as the HDAC-4-myogenin axis." (PMID 33375628, 2020). "Although we did not quantify these findings, similar results have been reported in an age-related sarcopenia caloric restriction rodent model.The increased activity of animals on CR may have contributed to the preservation of grip-strength as well as to myogenin upregulation." (PMID 30591621, 2018). "This study aimed to investigate the NUDT3 gene which has not been studied before, myogenin expression as evaluation tools and to identify new treatment approaches for delaying age-related sarcopenia." (PMID 38684784, 2024).
melanoma (16 papers, 2007 to 2025). A malignant, usually aggressive tumor composed of atypical, neoplastic melanocytes. "Hematolymphoid markers (CD45, B cell, and T cell), myogenic markers (myoglobin, desmin, myogenin), melanoma markers (HMB 45, melan A, tyrosinase) and Ewing’s sarcoma markers (CD99/MIC2) are absent in most ONB cases." (PMID 36452830, 2022). "Cells did not express Pan Cytokeratin AE1 and AE3 (carcinoma marker) and PS100 (melanoma marker) and had a strong expression of desmin and a focal expression of myogenin." (PMID 32438562, 2020). "Our case was S100 positive and negative for cytokeratins (excluding spindle cell carcinoma), smooth muscle markers (desmin, myogenin, and smooth muscle actin, excluding a smooth muscle tumour), and melanoma markers (HMB45 and Melan A)." (PMID 27672465, 2016). "We also noted absence of immunostain positivity for muscle markers (smooth muscle actin, desmin and myogenin), neural and melanoma marker (S-100), pankeratin (AE1/AE3), cytokeratin (CK5/6), CD57 and p63." (PMID 24715974, 2014). "Muscle markers (smooth muscle actin, desmin and myogenin), neural and melanoma marker (S-100), epithelial markers (AE1/AE3), CD57, CK5/6 and p63 were negative." (PMID 24715974, 2014). "However, only one of the two cases of congenital melanomas exhibited true rhabdomyosarcomatous dedifferentiation, as confirmed by immunohistochemical positivity for myogenin and myoD1." (PMID 40506928, 2025). "All other markers tested were negative (pan-melanoma, HMB45, Melan A, keratin AE1/AE3, desmin, alpha smooth muscle actin, h-caldesmon, CD34, p16, CD117, DOG1, myogenin, CD10, estrogen receptor (ER), progesterone receptor (PR), PAX8, WT1, synaptophysin, chromogranin A, CD99 and PRAME))." (PMID 39196362, 2024).
alveolar rhabdomyosarcoma (13 papers, 2008 to 2025). A rapidly growing malignant mesenchymal neoplasm. "Moreover myogenin and desmin immunopositivity was focal in comparison to alveolar rhabdomyosarcoma, where it is strong and diffuse." (PMID 24729898, 2014). "For example, in alveolar rhabdomyosarcoma (aRMS), the fusion oncogene PAX3::FOXO1 (or PAX7::FOXO1) binds SEs together with other MTFs, including MYOD, MYOG, and MYCN, to sustain proliferation, and their depletion leads to altered proliferation and cell death." (PMID 41444391, 2025). "For instance, the diagnosis of alveolar rhabdomyosarcoma (ARMS) is typically based on histopathological features, IHC results (most importantly desmin, MyoD1, and myogenin), and molecular results (RT-PCR for PAX3/PAX7–FOXO1 or FISH for PAX3/FOXO1 rearrangement)." (PMID 37621777, 2023).
Atrophy (13 papers, 2011 to 2025). Any weakening or degeneration, especially through lack of use. "Muscle atrophy was caused not only by the disruption of the IGF1/PI3K/Akt/mTOR pathway signaling but also by the observed decrease in myogenin expression in aged fish, which also contributes to muscle degeneration." (PMID 38892357, 2024). "Notably, MyoG is activated in the early stages of neurogenic muscle atrophy and failure in later downregulation is causally correlated with disease progression." (PMID 21892963, 2011). "In denervation-induced muscle atrophy, myogenin plays both a regulator of muscle development and an inducer of neurogenic atrophy." (PMID 39088432, 2024). "In this study, we investigated the role of FNDC5/irisin in muscle atrophy caused by hypoxia in vivo and in vitro and identified that the decreased expression of FNDC5/irisin and the myogenic factors Mrf4 and MyoG may be important reasons in hypoxia-induced muscle atrophy." (PMID 35055073, 2022). "Taken together, HDAC4 inhibition can alleviate denervation-induced muscle atrophy by reducing MYOG expression, and HDAC4 is also directly related to CDKN1A and SIK1 in skeletal muscle, which suggests that HDAC4 inhibitors may be a potential drug for the treatment of neurogenic muscle atrophy." (PMID 34276308, 2021). "Therefore, despite the fact that at 24 wks of age AR113Q male mice already show symptoms of the disease accompanied by signs of muscle atrophy and MyoG activation, the catabolic activity of muscle proteins mediated by atrogin-1, MuRF-1 and Cullin-3 ubiquitin ligases did not take place yet." (PMID 26490709, 2015). "Accordingly, in other models of muscle atrophy, an increase of HDAC4 and myogenin has been reported." (PMID 35408999, 2022). "Furthermore, in a TNF-α-induced atrophy model, both treatments of heat-killed HY7715 and HY7715-derived EVs restored the mRNA level MYOG to near-control levels, indicating their protective effect against inflammatory muscle damage." (PMID 40724603, 2025). "Our data indicate that MG132 prevent the DXR induced decrease in myogenin protein in H9c2 cells, suggesting that myogenin may play a role in DXR-induced atrophy." (PMID 26452256, 2015).